WDR4 (WDR4 tRNA N7-guanosine methyltransferase non-catalytic subunit)
Diseases named in the same sentence as WDR4 in open-access papers (continued):
Sharing a sentence is not in itself a finding about the gene and the disease.
cancer (62 papers, 2020 to 2025). A tumor composed of atypical neoplastic, often pleomorphic cells that invade other tissues. "Specifically, dysregulated m7G‐related enzymes, such as METTL1 and WDR4, are implicated in multiple cancer types." (PMID 40842081, 2025). "Studies have shown that WDR4 plays a crucial role in the development of malignant tumours, the aberrant expression of WDR4 is closely associated with tumour immunity and tumour mutation load." (PMID 38071502, 2024). "Pan-cancer analysis based on the TCGA database revealed aberrant expression of WDR4 in a broad spectrum of cancers and the association with inferior prognosis as well as tumor immunity." (PMID 36186903, 2022). "Previous research has established that the expression levels of the METTL1 and WDR4 components of the tRNA m7G methyltransferase complex are dramatically increased in human cancer samples and are negatively linked with patient prognosis." (PMID 35614925, 2022). "METTL1 and WDR4 are upregulated in various types of cancers, which are associated with poor prognosis in patients with cancers such as esophageal squamous cell carcinoma, intrahepatic cholangiocarcinoma, and nasopharyngeal carcinoma." (PMID 36313441, 2022). "Previous studies have reported that m7G-related regulators, in particular, METTL1 and WDR4, were associated with the prognosis of cancer patients." (PMID 36226166, 2022). "As the most studied methyltransferase involved in m7G-related processes, METTL1 usually forms a complex with WDR4, and its overexpression is often associated with some malignant tumors such as intrahepatic cholangiocarcinoma." (PMID 36532001, 2022). "According to the findings presented in the current report, the WDR4 level is associated with cancer immunity." (PMID 34282052, 2021). "Overexpression of METTL1/WDR4 leads to malignant transformation and tumorigenesis, promote cancer progression, and may be highly associated with m7G methylation modification of tRNAArgTCT-4-1." (PMID 39019857, 2024). "WDR4 levels are linked to cancer immunity and may be used as a prognostic biomarker for some cancers." (PMID 38436027, 2024). "Loss of METTL1 and WDR4 impairs cancer cell growth, tumorgenesis, and malignant transformation." (PMID 39850560, 2024). "In addition, the upregulated expression of METTL1/WDR4 complex in a variety of cancers is associated with malignancy and poor survival." (PMID 39850560, 2024). "Also, m7G methyltransferase WD repeat domain 4 (WDR4) expression was abnormal in various malignancies and was linked to OS and immune infiltration, according to a pan-cancer investigation." (PMID 35982949, 2022). "Because of its tumorigenic role, we analyzed five WDR4 gene polymorphisms in 313 pediatric patients and 1446 controls to explore whether functional WDR4 gene variants can modify individuals' cancer susceptibility." (PMID 36186903, 2022). "In addition, a close relationship was observed between WDR4 expression and mutations in 4 methyltransferases in several cancer types." (PMID 34282052, 2021). "More crucially, WDR4 is associated with immune infiltration, which suggests that WDR4 could be an immunotherapy target in cancers." (PMID 34282052, 2021). "In osteosarcoma, METTL1 and WDR4 mediate m7G modification of tRNA, enhancing mRNA translation and promoting cancer cell proliferation, migration, and chemoresistance." (PMID 41256854, 2025). "METTL1 and WDR4 promote cancer progression and poor prognosis by synergistically regulating the translation process." (PMID 41256854, 2025). "Previous studies have shown that METTL1 and WDR4 work together to add m7G modification in RNAs, and showed collaborative expression patterns in various cancers, including AML." (PMID 38268051, 2024). "The METTL1‐WDR4 complex, critical for tRNA stability and cancer development, relies on WDR4 to scaffold METTL1 and tRNA interaction." (PMID 39377984, 2024).
cancer (continued). "In a comprehensive analysis of pan-cancers, overexpression of METTL1 and WDR4 was correlated with more Tregs infiltration in diverse types of cancers." (PMID 38385078, 2024). "The silencing of METTL1 and WDR4 inhibits the proliferation, migration and invasion of cancer cells, while the forced expression of METTL1 contributes to tumor progression." (PMID 39850560, 2024). "Recent studies have found that METTL1/WDR4 mediated RNA m7G modification plays important biological roles in human malignancies, such as cancers in the liver, colorectal, esophageal, bladder, and lung." (PMID 38268051, 2024). "Another study demonstrated that the reduction of METTL1/WDR4 hinders the translational efficacy of the oncogene lysyl oxidase-like 2 (LOXL2), which is a cancer-causing enzyme that promotes the cross-linking of elastin and collagen in the extracellular matrix." (PMID 39019857, 2024). "The METTL1/WDR4 complex is capable of facilitating tRNA m7G modifications in several types of cancer cells." (PMID 39019857, 2024). "Overall, our result indicates a synergistic expression of METTL1/WDR4 genes in cancers, consistent with their functions as a complex." (PMID 39041608, 2024). "Utilizing expression profiles of 33 pan-cancer datasets from The Cancer Genome Atlas (TCGA) project, we observed aberrant expression of METTL1 and WDR4, known as m7G methyltransferase, across multiple cancer types." (PMID 38384713, 2024). "The expression levels of METTL1 and WDR4 are significantly increased in human cancers and correlated with poor prognosis." (PMID 38001714, 2023). "A recent report indicated that WDR4 plays a significant role in various kinds of malignant tumors for prognostic prediction and carcinoma drug resistance prediction after analyzing WDR4 through human pan-cancer." (PMID 36980210, 2023). "The expression levels of METTL1 and WDR4 significantly correlated with the sensitivity of cancer cells to antitumor drugs." (PMID 36635678, 2023). "To investigate the relationship between METTL1/WDR4 expression and immunotherapy response in pan-cancer, we first explored the correlation between the expression of METTL1 and WDR4 with the expression of immunoinhibitors in the TISIDB database." (PMID 36226166, 2022). "Pan-cancer analysis of 33 types of cancer indicated WDR4 was aberrantly upregulated in various cancers." (PMID 36186903, 2022). "In our study, we found that the expression levels of METTL1 and WDR4 were correlated with immunoinhibitors in pan-cancer datasets." (PMID 36226166, 2022). "More crucially, a link between WDR4 and immune infiltration suggests WDR4 as a target for immunotherapy in cancer." (PMID 36353111, 2022). "An analysis of human pan-cancer based on TCGA, GTEx, and CCLE databases has revealed that except for the TCGA kidney chromophobe cohort, WDR4 is continually upregulated in most cancer types." (PMID 36353111, 2022). "Pan-cancer analysis showed that WDR4 and METTL1 were closely related to cancer immune infiltration and were immunotherapy targets in patients, and the high expression of KIRC was associated with poor prognosis of patients." (PMID 36147333, 2022). "To explore the role of m7G tRNA modification in cancer, we first analyzed The Cancer Genome Atlas (TCGA) datasets and revealed that both METTL1 and WDR4 mRNAs are elevated in multiple cancers." (PMID 35304469, 2022). "WDR4, a member of the WD-repeat protein family, had been reported to play an important role in various kinds of malignant tumors." (PMID 36118897, 2022). "The results showed m7G methyltransferases, such as METTL1 and WDR4, were upregulated in a wide range of cancers, while RNA-binding and decapping enzymes (NUDT4, NUDT16, and NUDT10) were significantly downregulated." (PMID 35592316, 2022). "We aimed to conduct a comprehensive pan-cancer analysis to highlight the vital role of WDR4 in various types of malignancy." (PMID 34282052, 2021).
cancer (continued). "We conducted an in-depth analysis of three aspects of WDR4 expression patterns from 33 types of cancer and determined the value of WDR4 for prognostic prediction and carcinoma drug resistance prediction." (PMID 34282052, 2021). "The expression of WDR4 was significantly correlated with mutations in 5 MMR genes (MLH1, MLH2, MLH6, PMS2, EPCAM) in several cancer types." (PMID 34282052, 2021). "To assess the WDR4 gene expression levels at different cancer stages, we measured WDR4 expression levels in patients with stage I, II, III, and IV disease." (PMID 34282052, 2021). "We explored the expression level of WDR4 across 33 types of cancer and showed that WDR4 plays a significant role during cancer development." (PMID 34282052, 2021). "The involvement of WDR4 in tumour infiltration, microsatellite instability (MSI), and tumour mutational burden (TMB) was analyzed in various types of cancer." (PMID 34282052, 2021). "Recent publications have presented research showing that WD repeat domain 4 (WDR4) plays a significant role in various kinds of malignant tumours." (PMID 34282052, 2021). "Our current proteomic and loss-of-function analysis also indicated the essential roles of WDR4 in METTL1’s biological function in human cancer." (PMID 34285249, 2021). "We found by TIMER analysis that WDR4 levels are significantly associated with the infiltration of CD8+ and CD4+ T cells in in 21 types of cancer, B cells in 14 types, dendritic cells in 19 types, neutrophils in 15 types, and macrophages in 14 types." (PMID 34282052, 2021). "We discovered that the expression of WDR4 differed among various cancers, and abnormal expression of WDR4 was revealed to be a prognostic factor in certain types of malignancy by both Cox and KM survival analyses." (PMID 34282052, 2021). "The GTEX and CCLE analysis outcomes revealed that WDR4 gene expression levels were inconsistent across several cancer cell types." (PMID 34282052, 2021). "We obtained a large dataset of different types of cancer from the GTEX and TCGA databases to analyze the abnormal expression of WDR4 in different types of cancer." (PMID 34282052, 2021). "Similarly, in intrahepatic cholangiocarcinoma, METTL1 and WDR4 mediate m7G tRNA modification to enhance mRNA translation, promoting cancer progression and contributing to poor prognosis." (PMID 41256854, 2025). "Meanwhile, in cancer cells, METTL1/WDR4 mainly promotes the translation of genes related to cell proliferation, drug resistance, and angiogenesis by mediating m7G methylation of tRNA, so that cancer cells can better survive in the environment." (PMID 39019857, 2024). "The primary methyltransferase responsible for m7G modification is METTL1 (methyltransferase‐like 1), which targets mRNAs, while WDR4 (WD repeat domain 4) facilitates the binding of the heterodimeric complex to target mRNAs, influencing cancer development by regulating m7G methylation." (PMID 39445003, 2024). "In addition, METTL1/WDR4 regulates miRNA maturation in an m7G‐dependent manner, further contributing to cancer progression in lung and bladder cancer." (PMID 39041608, 2024). "Overexpression of m7G writers METTL1/WDR4 results in an increased abundance of m7G‐methylated tRNA, which in turn upregulates the translational efficiency of cell cycle‐regulating transcripts to drive cancer progression." (PMID 39041608, 2024). "Dysregulation of tRNA m7G modification by METTL1/WDR4 complex and consequent codon-biased translation may contribute to various types of cancers 44,45." (PMID 38385078, 2024). "In addition, METTL1 or WDR4 knockouts lead to impaired cell cycle gene function, affect tRNA function, ribosome suspension and mRNA translation, and inhibit cancer development." (PMID 39850560, 2024). "Higher expression of METTL1 and its cofactor WDR4 were significantly associated with poorer overall survival in LGG and LIHC, indicating an oncogenic role of the METTL1/WDR4 methyltransferase in these cancers." (PMID 39041608, 2024).
cancer (continued). "Furthermore, numerous recent studies have explored the relationship between m7G modification, METTL1/WDR4 complexes, and various diseases, particularly cancer." (PMID 38822363, 2024). "The collaborative expression between METTL1 and WDR4 was identified among various cancers." (PMID 38268051, 2024). "METTL1/WDR4 was reported to have a strong regulatory effect on cancer." (PMID 37006267, 2023). "WDR4 knockdown also suppressed the ability of H1299 cells to form soft-agar colonies and tumor spheres, the well-known assays for monitoring transformation ability and stemness property of cancer cells, respectively." (PMID 37821451, 2023). "We thus evaluated the influence of WDR4/PTPN23 axis on various cancer hallmarks." (PMID 37821451, 2023). "The expression of METTL1/WDR4 is abnormally elevated in most carcinomas, and by enhancing m7G tRNA expression, ribosome suspension is reduced, the efficiency of associated oncogenes’ mRNA translation is boosted, and downstream oncogenic signaling pathways like PI3K/AKT and MAPK are activated." (PMID 37710294, 2023). "Besides, a higher expression level of WDR4 is an adverse factor in many kinds of cancers, such as LUAD." (PMID 36353111, 2022). "Increased expression of WDR4 is regarded as an unfavorable prognostic biomarker in such cancers." (PMID 35590385, 2022). "Our thorough pan-cancer investigation illustrated the role of WDR4 in tumour cells and tissues." (PMID 34282052, 2021). "WDR4 was expressed in different cancer cell lines at inconsistent levels." (PMID 34282052, 2021). "Nevertheless, additional studies are needed to determine whether WDR4 can be used as a predictive biomarker for immunotherapy response in patients with these cancers." (PMID 34282052, 2021). "However, the expression profile of WDR4 is still unspecified, as is its significance in the analysis of human pan-cancer." (PMID 34282052, 2021). "Hence, the results of the current study provide a basis for further investigating the connection between WDR4 expression levels and cancer immunity." (PMID 34282052, 2021). "Notably, METTL1 and WDR4 are downregulated in cancers that originate from the endocrine system." (PMID 39041608, 2024). "In HCC, WDR4 interacts with METTL1 to synergistically regulate m7G mRNA modification, thereby promoting cancer progression." (PMID 41256854, 2025). "In a variety of cancers, m7G modification promotes cancer cell growth, proliferation and tumor formation through the METTL1/WDR4/Arg-TCT-4-1 axis." (PMID 38654314, 2024). "Therefore, the METTL1/WDR4 complex may be a potential target for cancer treatment." (PMID 39850560, 2024). "Studies have suggested a crucial function of m7G methyltransferase-related genes in the incidence and growth of cancer, especially the m7G regulatory factors METTL1 and WDR4." (PMID 39440068, 2024). "Histological staining showed that WDR4 and DDX20 were both upregulated in cancer tissues compared with normal tissues." (PMID 37783676, 2023). "Staining of two tissue sections from the same patient with either an anti-WDR4 or an anti-DDX20 antibody showed increased regional WDR4 and DDX20 levels in cancer tissues and a positive correlation between WDR4 and DDX20 expression." (PMID 37783676, 2023). "Using the cBioportal database, we examined the pan-cancer changes in METTL1 and WDR4 in the TCGA database." (PMID 36226166, 2022). "We also assessed the changes in the expression of m7G related regulatory genes in NSCLC with regards to the genetic and transcriptional aspects and evaluated the correlation of METTL1 and WDR4 expression with TMB, MSI and immunotherapy in pan-cancer." (PMID 36226166, 2022). "The increased expression of WDR4, METTTL1, NUDT1, and CYFIP2 enhanced the sensitivity of some anti-cancer drugs such as hydroxyurea, L-asparaginase, 5-fluoro-deoxy-uridine 10mer, and chelerythrine." (PMID 36226166, 2022).
cancer (continued). "In KIRC, the expressions of METT1 and WDR4 in cancer samples were significantly greater vs. healthy samples (p < 0.01), the greater the expressing levels of METT1 and WDR4, the worse the prognoses of KIRC sufferers." (PMID 35812727, 2022). "And in many kinds of cancer, imbalance of internal RNA m7G modification induced by dysregulation of METTL1 or WDR4 played an important role in tumorigenesis." (PMID 36396627, 2022). "It was discovered that the WDR4 levels were significantly correlated with the infiltration levels of CD4+ T and CD8+ T cells in 21 types of carcinoma, B cells in 14 types, neutrophils in 15 types, macrophages in 14 types, and dendritic cells in 19 types." (PMID 34282052, 2021). "An elevated protein expression of EIF4E, EIF4G3, LARP1, METTL1, NCBP1, NUDT4, and NUDT11 was discerned in the carcinoma samples, whereas the WDR4 expression was comparable between the tumor and adjacent non‐tumorous tissues." (PMID 40485623, 2025). "WDR4 plays an oncogenic role in HCC by positively regulating the expression of CCNB1 to induce the G2/M cell cycle transition and inhibit apoptosis, which promotes the proliferation ability of cancer cells." (PMID 37283791, 2023). "In addition, m7G genes such as EIF4E2, DCPS, WDR4, and METTL1 were highly correlated with RARA-AS1 in multiple types of cancer (greater than 10 types)." (PMID 37833349, 2023). "What’s more, the expression of some writer genes (METTL1 and WDR4) and reader genes (AGO2 and NCBP2) was significantly upregulated in most cancers, while the expression of some eraser genes (NUDT12 and NUDT16) and some reader genes (EIF4E3) were downregulated in most cancers." (PMID 36339001, 2022). "Recently, WDR4 has shown oncogenic potential in various adult cancers, but its roles in pediatric cancers have not been reported." (PMID 36186903, 2022). "Finally, the gene expression patterns of cancer cell lines from the Genomics of Drug Sensitivity in Cancer database were combined in order to comprehensively investigate the potential therapeutic benefit of the EIF4A1, EIF4G4, NCBP1, and WDR4 genes." (PMID 36816047, 2023). "Furthermore, functional annotation and pathway analysis of METTL1-associated proteins revealed that, in addition to METTL1 cofactor WDR4, two tRNA regulators, CTU2 and XPOT, may be functionally interconnected with METTL1 in human cancer." (PMID 34285249, 2021). "Furthermore, functional annotation and pathway analysis of METTL1-associated proteins revealed that, in addition to the METTL1 cofactor WDR4, RNA regulators and DNA packaging complexes may be functionally interconnected with METTL1 in human cancer." (PMID 34285249, 2021).